ABCB1 (ATP binding cassette subfamily B member 1)
Diseases named in the same sentence as ABCB1 in open-access papers (continued):
Sharing a sentence is not in itself a finding about the gene and the disease.
neuroblastoma (continued). "In the clinics, few neuroblastomas appear to express ABCB1 at diagnosis." (PMID 27517323, 2016). "Most strikingly (and in clear contrast to neuroblastoma cell lines with acquired resistance to other anti-cancer agents that are ABCB1 substrates), ABCB1 expression is an exclusive resistance mechanism in UKF-NB-3rSNS-032300nM cells and a predominant resistance mechanism in SHEPrSNS-0322000nM cells." (PMID 27517323, 2016). "Possibly, based on our currently presented data and previous studies, during chemo-immunotherapy applied in clinics with anti-GD2 ganglioside antibodies and chemotherapeutics, expression of ABCB1 transporter could be decreased, and neuroblastoma tumors might become more sensitive to chemotherapy." (PMID 41430389, 2025). "Notably, using expression data from the Individualized Therapy For Relapsed Malignancies in Childhood (INFORM) register (n = 1483), the expression of ABCB1 expression was significantly higher (P < 0.001) in relapsed neuroblastomas (n = 162) than in other relapsed entities." (PMID 36181342, 2023). "Reasons for this may include that survivin is not in all cell lines the major therapeutic target of YM155 as it is in neuroblastoma cells and/or that off-target resistance mechanisms, such as ABCB1 and SLC35F2 expression, may affect YM155 efficacy independently of the survivin status." (PMID 32357518, 2020). "Some clinical hints may also point towards a role of ABCB1 in acquired resistance in neuroblastoma." (PMID 32131402, 2020). "However, neuroblastoma cells with high ABCB1 levels were intrinsically resistant to YM15530." (PMID 28596528, 2017). "Consequently, statins enhance the intracellular accumulation of ABCB1 substrates like doxorubicin, which augments cytotoxicity in neuroblastoma and rhabdomyosarcoma cells and may provide the classical argument for usage in an anti-cancer therapy." (PMID 26319048, 2016). "Hence, the aim of this study was to show whether statin exposure to human neuroblastoma cells has an impact on endogenous dolichol levels and whether coadministration of dolichol could prevent ABCB1 downregulation and apoptosis." (PMID 26319048, 2016). "Additionally, there is evidence that ABCB1 can also be regulated by MYCN in neuroblastoma." (PMID 22458888, 2012). "To understand the involvement of ABC transporters in these vincristine-resistant neuroblastoma cells, we probed the expression levels of two well-characterized ABC transporters, ABCC1 and ABCB1." (PMID 40430358, 2025). "In contrast to ABCB1, ABCC1 (also known as MRP1) is generally accepted as prognostic factor in neuroblastoma." (PMID 32131402, 2020). "Hence, ABCB1 may represent an acquired resistance mechanism in neuroblastoma." (PMID 32131402, 2020). "In agreement with previous results, transduction of neuroblastoma cells with ABCB1 resulted in YM155 resistance, which was reduced by siRNA-mediated ABCB1 depletion." (PMID 32131402, 2020). "Here, we tested doxorubicin-loaded human serum albumin (HSA) nanoparticles in the neuroblastoma cell line UKF-NB-3 and its ABCB1-expressing sublines adapted to vincristine (UKF-NB-3rVCR1) and doxorubicin (UKF-NB-3rDOX20)." (PMID 31501742, 2019). "However, ABCB1 expression might represent an acquired resistance mechanism in neuroblastoma." (PMID 27517323, 2016). "In contrast, SHEPrSNS-0322000nM, the SNS-032-resistant sub-line of the neuroblastoma cell line SHEP, displayed low level SNS-032 resistance also when ABCB1 was inhibited." (PMID 27517323, 2016). "Therefore, we can conclude that PHLDA1 affected levels of the ABCB1 transporter in IMR-32 and CHP-134 neuroblastoma cells, which impacted on their sensitivity to doxorubicin." (PMID 41430389, 2025). "Our findings confirm 1) that YM155 is a drug candidate for neuroblastoma including therapy-refractory disease with the majority of cell lines being sensitive to clinically achievable YM155 concentrations and 2) that ABCB1 is an important determinant of YM155 sensitivity." (PMID 32131402, 2020).
neuroblastoma (continued). "Here, we investigated the effects of doxorubicin-loaded HSA nanoparticles on the viability of the neuroblastoma cell line UKF-NB-3 and its sub-lines adapted to doxorubicin (UKF-NB-3rDOX20) and vincristine (UKF-NB-3rVCR1), which both display ABCB1 activity and resistance to doxorubicin." (PMID 31501742, 2019). "The kinetics of cell surface reduction of ABCB1 is detected with MRK16 antibody in non-permeabilized SH-SY5Y neuroblastoma cells." (PMID 26319048, 2016). "The ABCB1 inhibitor verapamil sensitised ABCB1-expressing neuroblastoma cells to vincristine but not to flubendazole." (PMID 25644037, 2015).
Alzheimer disease (40 papers, 2006 to 2026). A progressive, neurodegenerative disease characterized by loss of function and death of nerve cells in several areas of the brain leading to loss of cognitive function such as memory and language. "The ABCB1 gene, encoding the ATP-dependent translocase ABCB1, plays a crucial role in the clearance of amyloid-beta (Aβ) peptides and the transport of cholesterol, implicating it in the pathogenesis of Alzheimer’s disease." (PMID 40168071, 2025). "At this point it is unclear if neuroinflammation contributes to the loss of ABCB1/ABCG2 proteins at the blood-brain barrier in Alzheimer’s disease." (PMID 36973040, 2023). "In the pathogenesis of Alzheimer’s disease, deficiency of P-glycoprotein with adenosine transferase protein (ABCB1), which is involved in the transport of β-amyloid from the brain tissue into the blood, plays an important role." (PMID 35408672, 2022). "In animal models of Alzheimer’s disease, the long-term deficiency of ABCB1 and ABCC1 has previously been found to accelerate neurodegeneration as a consequence of reduced β-amyloid elimination." (PMID 31572128, 2019). "The purpose of this study was to assess the effects of C1236T, G2677T/A and C3435T single-nucleotide polymorphisms in ABCB1 on blood–brain barrier P-glycoprotein function in healthy subjects and patients with Alzheimer's disease." (PMID 23067778, 2012). "In this case, ABCB1 is involved in Aβ transport, while disruption of this process may be associated with the development of Alzheimer’s disease." (PMID 36363640, 2022). "Nevertheless, some physiological or pathological conditions have been associated with a reduction in the abundance of ABCB1 and ABCG2 at the BBB as for instance healthy ageing or Alzheimer’s disease, which may raise the risk for ABCB1-mediated DDIs at the BBB and central side effects in the elderly." (PMID 34220523, 2021). "The Multi Drug Resistance (ABCB1) gene, encoding for P-gp, is highly polymorphic and this may result in a changed function of P-gp and may possibly interfere with the pathogenesis of Alzheimer's disease." (PMID 16999857, 2006). "While levels of proinflammatory mediators are increased, ABCB1/Abcb1 and ABCG2/Abcg2 expression and associated protein activity levels are decreased in animal models of Alzheimer’s disease as well as in patients with Alzheimer’s disease." (PMID 36973040, 2023). "Functional investigation of the ABCB1 expression is also essential in many diseases, including drug-resistant cancer, inflammatory conditions, or Alzheimer disease." (PMID 36142507, 2022). "Numerous studies have also demonstrated the importance of ABCB1 in the pathogenesis of Alzheimers disease." (PMID 36363640, 2022). "In a talk on sporadic proteopathies of the brain, Markus Krohn from Jens Pahnke`s group in Magdeburg reported on the role of ABC transporters in Alzheimer`s disease with a special focus on the effect of ABCB1 and ABCC1 regarding clearance mechanisms." (PMID 24330587, 2013). "Since reducing ABC transporter activity could exacerbate conditions such as Alzheimer’s disease, including prodromal stages, where ABCB1 activity is critical for clearance of Aβ from the brain, chronic downregulation of ABC transporters could bear risks." (PMID 36973040, 2023). "In models of Alzheimer’s disease, concerns have been raised that the long-term inhibition of ABCB1 and ABCC1 may exacerbate neurodegeneration as a consequence of reduced β-amyloid clearance." (PMID 31572128, 2019). "Furthermore, restoration of mdr-1 P-glycoprotein/Abcb1 at the BBB by PXR (Pregnane X Receptor) agonist reduced brain Aβ load in a mouse model of Alzheimer's disease." (PMID 23432917, 2013). "Amyloid beta (Aβ) deposition in Alzheimer’s disease has been shown to be inversely correlated with ABCB1 expression in the brains of elderly people without dementia, which may indicate that age-related ABCB1 deficiency may be involved in the pathogenesis of Alzheimer’s disease." (PMID 36363640, 2022).
Alzheimer disease (continued). "Interestingly, the overexpression of ABCB1 and ABCA2 is connected with various neurodegenerative pathologies, especially Alzheimer’s disease." (PMID 32466263, 2020). "Moreover, ABCB1 and possibly ABCG2 play a role in Alzheimer’s disease (AD) by mediating the brain clearance of beta-amyloid (Aβ) across the BBB." (PMID 33153231, 2020).
chronic myeloid leukemia (36 papers, 2012 to 2026). "In chronic myeloid leukemia, a relevant decrease in imatinib clearance was associated with variant alleles of ABCB1 and SLCO1B3." (PMID 35456712, 2022). "This ABCB1 sSNP has been reported to be associated with tacrolimus response in ulcerative colitis 26, imatinib response in chronic myeloid leukemia 27, and paclitaxel sensitivity in different cancer cells." (PMID 32226509, 2020). "CYP3A5*3 and ABCB1 C3435T variants influence clinical outcomes and plasma concentrations of Imatinib in Nigerian patients with chronic myeloid leukaemia." (PMID 32858798, 2020). "Mutation in ABCB1 efflux transporters is one of the known mechanisms of resistance to imatinib in chronic myeloid leukemia patients." (PMID 31759356, 2019). "This study was aimed to investigate the association of ABCB1 C1236T polymorphism in Indonesian chronic myeloid patients with molecular response to imatinib treatment." (PMID 31759356, 2019). "The most common ABCB1 variants are 1236C > T, 2677G > T, 3435C > T and have been associated with clinical response to imatinib in chronic myelogenous leukaemia (CML) in some studies." (PMID 27405085, 2016). "ABCB1 overexpression is a pivotal mechanism of resistance to tyrosine kinase inhibitors (TKIs) in Chronic Myeloid Leukemia (CML), impacting drugs such as imatinib, nilotinib, and dasatinib." (PMID 40429842, 2025). "For example, nilotinib (Tasigna), a Bcr-Abl inhibitor approved for therapy of chronic myelogenous leukemia (CML) has been shown to inhibit the function of ABCB1-, ABCG2-, and ABCC10 transporters and reverses drug resistance." (PMID 35327403, 2022). "ABCB1 promoter is differentially methylated at its GC-100 box in K562 cells compared with Lucena cells, and in chronic myeloid leukemia (CML) patients with different response to IM." (PMID 26703582, 2015). "This study aimed to explore the influence of SLC22A1, PXR, ABCG2, ABCB1 and CYP3A5*3 genetic polymorphisms on imatinib mesylate (IM) pharmacokinetics in Asian patients with chronic myeloid leukemia (CML)." (PMID 23272163, 2012). "Indeed, glycosphingolipid biosynthesis was shown to regulate drug sensitivity in clinically relevant models of drug-resistant chronic myeloid leukemias, through modulation of both the expression and activity of the drug efflux proteins ABCB1 and ABCC1." (PMID 36983080, 2023). "Furthermore, ABCB1 is highly overexpressed in doxorubicin-resistant cell lines, and β-catenin depletion in a chronic myeloid leukemia cell line leads to reduced ABCB1 mRNA expression, whereas Wnt signaling increases ABCB1 mRNA expression." (PMID 28757546, 2017). "In conclusion, our result suggested that the C1236T variant of ABCB1 might not have an association with molecular response to imatinib in chronic myeloid leukemia patients." (PMID 31759356, 2019). "Tyrosine Kinase Inhibitors (TKIs), like nilotinib and dasatinib, are effective treatments available for Chronic Myeloid Leukaemia (CML) and found to interact with ABCB1 and ABCG2." (PMID 33799762, 2021). "Reports started with ABCB1 and ABCG2 overexpression in Philadelphia chromosome-positive chronic myeloid leukemia cells as a consequence of imatinib selection." (PMID 27367030, 2016).
pancreatic cancer (36 papers, 2010 to 2025). "The TT genotypes of G2677T and C3435T in ABCB1 gene were associated with lower risk of developing pancreatic cancer (P = 0.013, OR = 0.35 and P = 0.015, OR = 0.29, resp)." (PMID 24883056, 2014). "In this study, the ABCB1 2677TT and 3435TT genotypes were found to be associated with reduced risk of developing pancreatic cancer in the whole study population and European Americans." (PMID 24883056, 2014). "The ABCB1 2677TT-3435TT haplotype was significantly associated with reduced risk of developing pancreatic cancer (OR 0.27, 95% CI 0.08 to 0.92, P = 0.037) in European Americans, and the expression of ABCB1 was also lower compared to the other haplotypes." (PMID 24883056, 2014). "Any of these mechanisms could possibly explain the striking finding from this study that lower expression levels of ABCB1 in the normal 2677TT and 3435TT carriers are associated with reduced risk of developing pancreatic cancer." (PMID 24883056, 2014). "The ABCB1 2677-3435 haplotypes in these pancreatic cancer cell lines might be associated with other unknown mechanisms that affect the cells' sensitivity to gemcitabine." (PMID 24883056, 2014). "P-glycoprotein (P-gp, ABCB1) increases in many gemcitabine-resistant cell lines and pancreatic cancer samples, and molecular docking plus lab tests show it can bind and pump out gemcitabine." (PMID 41293424, 2025). "ABCG2 and ABCB1 have been suggested as important mediators of resistance to chemotherapy (CTx) in pancreatic cancer (PC)." (PMID 40548120, 2025). "Among these transporter proteins, the significant overexpression of ABCB1 was found to be concomitant with the proliferation of resistant CD44 cells, suggestive of the regulatory role of CD44-ABCB1 interaction in GEM efflux in pancreatic tumor cells." (PMID 34453639, 2021). "Controversially, the stimulation of TAS2R38 by PTC, as specific agonist of TAS2R38, or AHL-12, a bacterial molecule, induced the upregulation of the protein ABCB1, which fosters multidrug resistance in a pancreatic cancer cell line." (PMID 34885005, 2021). "Next we investigated the potential effect of ABCG2 inhibitors (Ko143) and ABCB1 inhibitors (verapamil) on the intracellular accumulation of gemcitabine to further confirm ABC transporter function on gemcitabine efflux in pancreatic cancer cells." (PMID 31652737, 2019). "SP cells isolated from the PANC1, pancreatic cancer cell line, have been found to express both ABCB1 and ABCG2." (PMID 26649310, 2015). "Previous work investigated that chemoresistance in pancreatic cancer cells was via regulating the expressions of MDR genes including ABCB1, ABCC1, ABCC3 and ABCC5." (PMID 26709920, 2015). "A cell viability assay, using standard pancreatic cancer cell lines, revealed that the ABCB1 2677TT-3455TT haplotype was more sensitive than the other haplotypes to gemcitabine." (PMID 24883056, 2014). "In fact, this result is consistent with our observation that fewer carriers of ABCB1 2677TT and 3435TT developed pancreatic cancer." (PMID 24883056, 2014). "In conclusion, our study described that silencing of TM4SF1 sensitized pancreatic cancer cells via downregulating ABCB1 and ABCC1 to kill by treatment with gemcitabine may be of particular translational significance." (PMID 26709920, 2015). "This study aimed at determination whether Q sensitizes cells of pancreatic carcinoma resistant cell line to action of DB by decreasing membraneous expression of P-gp, blocking its transport functions and affecting expression of ABCB1 gene." (PMID 20335952, 2010). "However, our study found that an up-regulated level of ABCB1 could improve the survival rate of pancreatic cancer." (PMID 37857015, 2023). "Therefore, we next assessed whether coix seed extract could modulate the drug efflux effect regulated by the ATP binding cassette transporters ABCG2 and ABCB1 in pancreatic cancer cells in vitro and in vivo." (PMID 31652737, 2019).
pancreatic cancer (continued). "The lack of protective genotype/haplotype, ABCB1 2677TT and 3435TT, may contribute to a higher susceptibility of African Americans to pancreatic cancer and increased likelihood of gemcitabine chemoresistance, thus poor prognosis." (PMID 24883056, 2014). "Since the substrate sets of ABCA1-2, ABCB1, ABCC5, and ABCG2 overlap, the general effect of SOX9 suppression on overall or partial drug resistance of pancreatic cancer cells in context of these ABC proteins cannot be predicted with certainty." (PMID 40141294, 2025). "For example, MUC1 has been shown to act as a transcriptional inducer of ABCC1 in pancreatic cancer, whereas in cervical cancer, MUC1 promotes ABCB1 expression through an EGFR-dependent mechanism." (PMID 38254882, 2024). "In conclusion, cancer stem-like cells play a pivotal role in acquiring multidrug resistance in pancreatic cancer; CD44+ cells in particular, which repopulate after chemotherapy, were responsible for the chemoresistance mediated by ABCB1." (PMID 37108495, 2023). "Meanwhile, ABCB1 and ABCG2 were found to be an important indicator of drug-resistance in pancreatic cancer." (PMID 31652737, 2019). "In order to further confirm the protein expression results in vitro, the immunohistochemical analysis was assessed for ABCB1 and ABCG2 expression levels in pancreatic tumor tissues from xenograft mice." (PMID 31652737, 2019). "Our current study identified the change of exosome and lipid metabolism-related genes with clinical value, and the 7-gene (ABCB1, CAP1, EGFR, ITGB1, MAPK1, PPARG, SNCA) prognostic formula is a novel and reliable predictive index in pancreatic cancer and other multiple cancers." (PMID 37857015, 2023). "Moreover, the mRNA level of ABCB1 and SNCA were identified with significant downregulation in pancreatic cancer cell lines compared to normal pancreatic cells." (PMID 37857015, 2023). "Expansion of a stem cell-like population of cells as well as a ABCB1+ cell population was also reported in pancreatic cancer, in which Notch was activated by the adipocyte hormone leptin, though co-staining for stem cell markers and ABCB1 was not performed." (PMID 35582031, 2021). "In addition, ABCB1 and ABCG2 transporter mainly expresses in cell membranes and cytoplasm in pancreatic cancer cells." (PMID 31652737, 2019). "However, the role of ABCB1 in resistance to paclitaxel has not been addressed in pancreatic cancer." (PMID 38163893, 2024).